CRP (C-reactive protein)
Diseases named in the same sentence as CRP in open-access papers (continued):
Sharing a sentence is not in itself a finding about the gene and the disease.
Sepsis (continued). "A simpler six-parameter method using age, immunosuppression, GCS score, body temperature, CRP and bilirubin on admission predicts 30-day mortality upon ICU admission for sepsis patients just as well as SAPS-3." (PMID 37841294, 2023). "In our cohorts, NS patients showed statistically significant higher levels of inflammation, coagulation, and sepsis markers (such as NLR, CRP, ferritin, IL-6, TNF-α, D-dimer, fibrinogen, PCT, and LDH) compared to S patients." (PMID 36781931, 2023). "In our study, CRP, INR, PT, NLR, and PNI were observed to be independent predictors of sepsis in patients with DFU." (PMID 38026334, 2023). "When the analysis included all sepsis alert patients and all patients with infections, p-calprotectin had significantly larger AUC than PCT and NLR and tended to have larger AUC than CRP." (PMID 36774492, 2023). "In subgroup analyses through our meta-analyses, a significantassociation of preoperative leukocyte count, CRP, NLR, and PLR with postoperative sepsis inpatients who undergo PCNL was reported in almost all of the included studies." (PMID 37426769, 2023). "Its steep increase allows sepsis detection up to 72 h before clinically overt deterioration, thus outperforming CRP- and PCT-based protocols for sepsis diagnosis." (PMID 37176638, 2023). "Receiver operating characteristic (ROC) curves were plotted to assess the accuracy of PCT, CRP, and NLR in diagnosing sepsis among the entire study lot." (PMID 37892278, 2023). "Point-of-care diagnostic tests involving the detection of inflammatory markers such as C-reactive protein (CRP) and procalcitonin are used in the diagnosis of lower RTI and sepsis, respectively." (PMID 38283945, 2023). "Several studies have reported that MR-proADM has a higher prognostic value for sepsis than biomarkers such as procalcitonin (PCT) and C-reactive protein (CRP)." (PMID 37685368, 2023). "In this study, we found that betaine given by ip injection in the sepsis group decreased the levels of pro-inflammatory cytokines (TNF-α, CRP, IL 1-β, IL-6) and oxidative stress biomarkers (MDA, LA) and increased PaO2." (PMID 37970921, 2023). "CRP, procalcitonin, and DNI levels in the sepsis group were higher than those in the non-sepsis group (103.0 ± 91.6 vs. 34.9 ± 45.7 (p = 0.000), 8.2 ± 21.1 vs. 1.8 ± 6.8 (p = 0.004), and 6.7 ± 7.8 vs. 2.1 ± 2.2 (p = 0.000))." (PMID 38137411, 2023). "Compared with sepsis, the three proteins with the largest decrease in HLH were protein sidekick-1 (SDK1), serum amyloid A-1 protein (SAA1), and C-reactive protein (CRP )." (PMID 37653176, 2023). "Salivary CRP cut-off scores were comparable to serum CRP in terms of sensitivity, specificity, PPV, NPV, and accuracy in predicting culture-positive sepsis." (PMID 36900011, 2023). "This meta-analysis aims to determine C-reactive protein (CRP),neutrophil to lymphocyte ratio (NLR), and platelet to lymphocyte ratio (PLR) obtainedpreoperatively used to predict postoperative sepsis after PCNL." (PMID 37426769, 2023). "The 351 included sepsis alert patients had the following biomarker results (medians, IQR): p-calprotectin 2.2 mg/L (IQR 1.1–3.8 mg/L), CRP 67 mg/L (IQR 23–146 mg/L), PCT 0.6 μg/L (IQR 0.2–6.0 μg/L), and NLR 11.4 (IQR 6.1–18.7)." (PMID 36774492, 2023). "The levels of CRP, PCT, and IL8 can take time to rise significantly following the onset of infection or sepsis." (PMID 38053180, 2023). "ROC curve analysis showed that APOA5, CRP, copeptin, and PSP predicted pediatric sepsis with high sensitivity." (PMID 36755189, 2023). "CBC with differential and C-reactive protein (CRP) are additional crucial lab tests to get and are routinely collected on a serial basis; however, these indices are weak at diagnosing newborn sepsis and are better suited for ruling it out." (PMID 38012554, 2023).
Sepsis (continued). "Logistic regression analysis was further employed to investigate the independence of NLR in predicting sepsis among our study groups, with sepsis as the dependent variable and NLR, PCT, and CRP as independent variables." (PMID 37892278, 2023). "Biochemical analysis and white blood cell count depicted that sepsis-affected neonates had increased PCT, CRP, ALT, and neutrophil count and lowered levels of ALB, lymphocyte count, and LCR." (PMID 37197571, 2023). "Among the sepsis biomarkers, IL-6 had the highest AUC (0.778), followed by PCT (0.744), presepsin (0.685), and CRP 0.528." (PMID 37324133, 2023). "Some of the existing biomarkers for infection diagnosis include C-reactive protein (CRP) and procalcitonin (PCT) for sepsis, calprotectin for acute respiratory infections, and several others." (PMID 36794396, 2023). "In patients with culture-confirmed sepsis after DOL 7, serum IL-6 has its peak on the day of a positive culture, while CRP needs 36 h to reach its peak." (PMID 36216867, 2023). "C-reactive protein (CRP) and procalcitonin (PCT) are among the most extensively studied biomarkers for sepsis diagnosis." (PMID 37147598, 2023). "In patients with culture-confirmed sepsis on DOL 1, serum IL-6 starts high from its peak and declines until 48 h of life while CRP starts increased but needs up to 48 h to reach its peak." (PMID 36216867, 2023). "Conventional inflammatory biomarkers, such as CRP and PCT, have been extensively studied and applied in patients with sepsis." (PMID 37147598, 2023). "PCT is also more effective than CRP and WBC in predicting sepsis, with a mean sensitivity of 0.77 (95% CI 0.72–0.81) and specificity of 0.79 (95% CI 0.74–0.84)." (PMID 37109763, 2023). "Using specific ELISA parameters, we analyzed the levels of porcine CRP, haptoglobin, IL-4, IL-10, PGE2, TGF-ß and porcine alpha-1 acid glycoprotein, as we considered these to be fundamental sepsis biomarkers according to existing clinical research." (PMID 38087374, 2023). "The combination of four proteins was exhibited a ROC curve with an AUC of 0.772 in diagnosing sepsis, which was higher than the AUC of PCT (0.717) and CRP (0.706)." (PMID 34825737, 2022). "C-reactive protein (CRP) and procalcitonin (PCT) are two biomarkers used to diagnose sepsis in clinical practice." (PMID 35867213, 2022). "Overall, the current study showed reductions in cytokine levels, CRP, and PCT levels among ICU patients diagnosed with sepsis or septic shock following cytokine hemadsorption therapy." (PMID 35317038, 2022). "SAA1;SAA2, CRP, ITIH3, SERPINA1 are acute phase proteins that are also dysregulated in other inflammatory states including sepsis." (PMID 36812516, 2022). "Pro-inflammatory cytokines and inflammatory biomarkers, such as C-reactive protein (CRP), IL-1, IL-6 and TNF-α, increase after the development of sepsis." (PMID 35193654, 2022). "In a prospective study including 68 newborns with early-onset sepsis (EOS) and 83 newborns as a control group, it was demonstrated that IL-6, TNF-α, HSP70, PCT, and CRP together with MMP-8 can be used as a predictive biomarker of EOS." (PMID 36613805, 2022). "Similar to serum CRP, LBP production increases due to pro-inflammatory cytokines in inflammatory states such as sepsis and multiple organ failure." (PMID 35203200, 2022). "Presepsin has been reported to be a useful marker to diagnose sepsis, similar or superior to procalcitonin (PCT) and C-reactive protein (CRP)." (PMID 35273185, 2022). "C‐reactive protein (CRP) and white blood cells (WBC) are commonly measured in pregnant women with suspected sepsis." (PMID 35866444, 2022). "While there are studies and commercial strips for PCT or CRP detection, limited options are available to simultaneously detect and quantify PCT and CRP over a dynamic range observed in sepsis patients, especially for high-dose CRP in the hook effect range." (PMID 35149284, 2022).
Sepsis (continued). "C‐reactive protein (CRP), interleukin‐27 (IL‐27), and neutrophil CD64 (nCD64), with different sensitivity and specificity, were infection markers for early diagnose of sepsis." (PMID 34825737, 2022). "Inflammatory factors such as NLR, CRP, and PCT have important clinical applications in the assessment of the extent of disease and prognosis of patients with bloodstream infection and sepsis." (PMID 35345421, 2022). "Similar correlations between eCIRP and biomarkers for severity, i.e., CRP, IL-6, and procalcitonin (PCT) has been observed in sepsis, community acquired pneumonia, and acute pancreatitis." (PMID 35967397, 2022). "Biomarkers secreted in the blood in sepsis condition were also targeted by various research groups, for example, a PMMA-based POCT device was fabricated to detect C-reactive protein (CRP) and neopterin (NP)." (PMID 35624657, 2022). "Prior studies have reported that the acute phase proteins CRP and PCT are useful markers for sepsis." (PMID 35337261, 2022). "Lnc‐GAS5 negatively linked with Th17 cells and IL‐17A; negatively correlated with SOFA score, SOFA‐Respiratory system score, SOFA‐Coagulation score and SOFA‐Renal system score; negatively related to CRP and APACHE II score in sepsis patients." (PMID 35325494, 2022). "For example, the capacitive detection of C-reactive protein (CRP), a biomarker for cardiovascular disease risks, sepsis and other tissue inflammation was extensively studied." (PMID 36671852, 2022). "Increased concentrations of soluble P2X7 receptor in the blood have been described as positively correlating with the concentration of CRP, with the soluble P2X7 receptor being elevated during infection and sepsis, and during temporal lobe epilepsy." (PMID 35663992, 2022). "Several biomarkers such as C-reactive protein (CRP), procalcitonin (PCT), and white blood cells (WBCs) can serve as predictors of sepsis." (PMID 36475186, 2022). "When IL-6 is combined with additional sepsis markers as TNF-a and CRP, the sensitivity and NPV for diagnosing EOS improves." (PMID 35449688, 2022). "Several studies systematically evaluated the clinical value of PCT and CRP in the diagnosis of adult patients with sepsis which demonstrated a higher diagnosis accuracy and specificity of PCT than CRP." (PMID 36167572, 2022). "Procalcitonin (PCT) and C-reactive protein (CRP) have both been used as biomarkers to infer bacterial infections, particularly in the context of sepsis." (PMID 35149284, 2022). "All studies involved operated patients and the measurement of CRP and PCT postoperatively during their in-hospital/ICU stay and their role in patients developing sepsis and SIRS." (PMID 36475186, 2022). "Age, CRP, PCT, APACHE II, SOFA, LC3II, Beclin-1, RAB7, LAMP2, and p62 are related to the death of patients with sepsis and ARDS." (PMID 35371338, 2022). "One parameter is C-reactive protein (CRP), which is an acute-phase protein that can be severely elevated in patients with SIRS or sepsis as compared to healthy patients." (PMID 36713872, 2022). "Several potential biomarkers for monitoring sepsis have been investigated, including white blood cell count (WBC), C-reactive protein, (CRP), lactate, and procalcitonin (PCT)." (PMID 36050405, 2022). "Traditional biomarkers for sepsis, such as procalcitonin (PCT), IL-6, and c-reactive protein (CRP) have limited discriminative value due to inadequate specificity and sensitivity." (PMID 35187084, 2022). "Significantly higher concentrations of CRP and PCT were found in the sepsis than in the non-sepsis group at admission, with peak values of PCT noted at admission whereas CRP and WBC increased significantly during the first 24 h among the septic patients." (PMID 36050405, 2022). "ROC curve analysis showed that CAR had a higher discriminatory power than CRP, ALB, and PCT in predicting sepsis in neonates with pneumonia." (PMID 35873709, 2022).
Sepsis (continued). "C-reactive protein (CRP), interleukin-6 (IL−6) and procalcitonin (PCT) have been widely used to facilitate sepsis diagnosis, with limited results." (PMID 36431277, 2022). "Lnc‐ITSN1‐2 had a positive connection with CRP (rs = 0.338, p = 0.001) and APACHE II score (rs = 0.231, p = 0.024) in sepsis patients." (PMID 35243686, 2022). "Existing biomarkers of sepsis such as C-reactive protein (CRP), procalcitonin (PCT), and lactate tests are ordered only if the clinician has already observed a high index of clinical suspicion of sepsis." (PMID 34983430, 2022). "Beyond procalcitonin, other frequently studied biomarkers such as CRP, IL-6, IL-8, IL-10, and TNF-α have had much less success predicting infection and sepsis." (PMID 39604183, 2022). "Presepsin is a relatively newly developed biomarker for sepsis compared to other biomarkers such as PCT, CRP, cytokine, chemokine, and growth factors." (PMID 35870180, 2022). "Evaluation of the ability of CRP, PCT, suPAR, and neutrophil/lymphocyte ratio (NLCR) to predict blood stream infection and sepsis in an emergency setting." (PMID 36420338, 2022). "Various biomarkers, such as levels of C-reactive protein (CRP), procalcitonin (PCT), or interleukin-6 (IL-6), have been implemented in the past to diagnose suspect sepsis." (PMID 35615626, 2022). "Daily values of WBC, CRP and body temperature were recorded following ASCT in 580 days of 39 FN episodes, verifying fever onset and eventual sepsis." (PMID 35054007, 2022). "Sepsis was classified according to the SIRS criteria, and CRP, WBC, PCT, and PSEP levels were measured." (PMID 35666350, 2022). "Different biomarkers have been used for diagnosis of sepsis and monitoring of treatment, such as proclcitonin (PCT), C-reactive protein (CRP), cytokines, and human leukocyte antigen DR (HLA-DR)." (PMID 35739592, 2022). "Multiplex detection of C-reactive protein (CRP), procalcitonin (PCT), and interleukin-6 (IL-6) is a reliable method for accurately diagnosing infections and sepsis." (PMID 35144683, 2022). "One child (case 5) with sepsis and systemic fungal infection was also diagnosed with MIS-C with raised CRP, procalcitonin, troponin, D-dimers, and fibrinogen." (PMID 35308495, 2022). "The extracted significant factors, in both overall and surgical cases, were cardiovascular and digestive organ, complication of sepsis, SOFA score, catecholamine index, case of continuous hemodiafiltration, lactate and CRP." (PMID 35982206, 2022). "It was observed that while initial PCT and CRP values were comparable, the raised PCT value by Day three of suspected sepsis is highly sensitive, specific, and accurate for surgical neonatal sepsis." (PMID 36158418, 2022). "WBC and CRP and PCT levels have been used in the past to determine the severity of infection and sepsis in patients with odontogenic infection, but PSEP was also found to have diagnostic value in this study." (PMID 35666350, 2022). "In the present studies, it is not surprising to find significant elevation in the serum level of CRP, PCT, and WBC in the newborn with sepsis." (PMID 35664882, 2022). "One study observes that miR-451a is positively related to CRP and septic organ injury as shown by SOFA and APACHE II scores in patients with sepsis." (PMID 35992658, 2022). "Laboratory evidence of systemic inflammation was common (median CRP 220 mg/L [IQR 175–292]; median neutrophils 9.8 × 109/L [6.9–13.9]) but overt sepsis (qSOFA ≥2) was uncommon (7/60; 11.7%)." (PMID 34727367, 2022). "C-reactive protein (CRP), white blood cell count (WBC), procalcitonin (PCT), and presepsin (PSEP) can be used to evaluate the severity of inflammatory status and sepsis in patients in the early stages of visiting the emergency room." (PMID 35666350, 2022). "We found that sepsis patients had significantly higher levels of WBC, Neutrophil percent, C-reactive (CRP), procalcitonin (PCT), lactate, lymphocyte percent, LDH, BUN, and proBNP." (PMID 35363162, 2022).
Sepsis (continued). "Sepsis and inflammatory biomarkers rose (PCT, Procalcitonin, 12.164 ng/mL, CRP, C-Reactive Protein, 133.71 mg/L), although blood cultures yielded persistently negative results." (PMID 36324062, 2022). "Patients in the sepsis group had higher PCT, WBC, CRP, IL-1β, IL-2, IL-6, IL-8, IL-10, IL-12, IL-17, IFN-γ, and SOFA scores than those in the infection group, and the difference was statistically significant (P < 0.05)." (PMID 35937269, 2022). "IL-6, IL-8 and IL-10 peak as soon as sepsis is suspected, while PCT and CRP react later, with concentration peaks at 8–16 and 16–24 h, respectively." (PMID 35626858, 2022). "FTB, DNase1, FTB + DNase1, Cl-amidine, and FTB + Cl-amidine treatment lowered the levels of CRP, IL-6, IL-1β, and TNF-α in rats with sepsis." (PMID 36408247, 2022). "Based on ROC curve analyses, the diagnostic performance of chemerin (AUC 0.78, 95% CI 0.69–0.87) was similar to C-reactive protein (CRP) (AUC 0.78, 95% CI 0.68–0.87) in discriminating sepsis severity." (PMID 35204801, 2022). "nCD64 index combined with CRP was superior to CRP, PCT, nCD64 index and nCD64 index plus PCT in predicting 28-day mortality in sepsis." (PMID 35907785, 2022). "Inflammatory factors, such as neutrophil lymphocyte ratio (NLR), CRP, and PCT, have important clinical applications in assessing the extent of disease and prognosis of patients with bloodstream infection and sepsis." (PMID 36148158, 2022). "Current biomarkers, such as C-reactive protein (CRP) and procalcitonin (PCT), have been widely applied in the clinic to monitor sepsis." (PMID 35907902, 2022). "Laboratory markers such as C-reactive protein (CRP), neutrophil to lymphocyte ratio (NLR), and lactate have been widely used to aid in the diagnosis of sepsis in clinical settings." (PMID 36035420, 2022). "Septic patients were regrouped by these cutoff values to validate their prediction efficacy for 28-day mortality, as well as the severity at sepsis onset, including SOFA score, APACHE II score, and serum CRP and lactate levels." (PMID 35592322, 2022). "In one study, levels of presepsin, PCT, CRP, and WBC were higher in sepsis patients than in a SIRS group with AUROC values of 0.954 (presepsin), 0.874 (PCT), 0.859 (CRP), and 0.723 (WBC)." (PMID 34991675, 2022). "In this study, the average levels of CRP and PCT in patients with severe sepsis, or septic shock, were higher than those in the sepsis group, and the differences of PCT was statistically significant in univariate analysis (P = 0.000)." (PMID 35346141, 2022). "Further, more data is needed to define the optimal cut-off values of CRP and PCT for neonatal sepsis for surgical and medical neonates." (PMID 36158418, 2022). "Blood cultures, CRP, and PCT on Day one (PCT1) and Day three (PCT3) of suspicion of sepsis were evaluated." (PMID 36158418, 2022). "During thrombocytopenia, CRP values >200 mg/L and PCT values >10 μg/L often indicate severe infection resulting in sepsis, hemodynamic disorders, organ dysfunction, and poor prognoses." (PMID 36684358, 2022). "The primary outcomes extracted from the finalized research papers were the role of CRP and PCT levels, development of SIRS, sepsis, or death." (PMID 36475186, 2022). "We found that sepsis patients had significantly higher levels of WBC, neutrophil percent (N%), C-reactive (CRP), procalcitonin (PCT), lactate, and lymphocyte percent (L%)." (PMID 35363162, 2022). "C-reactive protein (CRP) and procalcitonin (PCT) are biomarkers used in the basic laboratory tests for the diagnosis of sepsis." (PMID 36538555, 2022). "There is a paucity of evidence to support using lactate or CRP to make decisions about antibiotics around the time of delivery but, as lactate is rarely higher than 4 mmol/l, this upper limit may still represent a useful severity marker for the investigation and management of sepsis in labour." (PMID 35866444, 2022).